BCL2 (BCL2 apoptosis regulator)
Diseases named in the same sentence as BCL2 in open-access papers (continued):
Sharing a sentence is not in itself a finding about the gene and the disease.
cancer (continued). "Pro-survival genes such as BCL-2 and MCL-1 have been observed to be redundantly regulated by multiple miRNAs in cancer; inappropriate silencing of these molecules by miRNAs in AD could exacerbate neurodegeneration." (PMID 23335942, 2012). "The downregulation of apoptosis-related pathway is not surprising, since it has been suggested that the Bcl-2 signaling pathway of apoptosis plays an important role in drug resistance in cancer cells." (PMID 22737246, 2012). "Furthermore, the expression of bcl-2 was higher (OR = 1.77, CI = 1.01-3.23) and that of HER2/neu was lower in screen-detected cancers compared with symptomatic ones." (PMID 23244222, 2012). "Several components of apoptosis signaling pathways may be exploited as targets for the development of experimental cancer therapies, for example the TRAIL system, IAP proteins or anti-apoptotic Bcl-2 proteins." (PMID 24212616, 2011). "No significant decline in the levels of Mcl-1 and Bcl-2 was observed in the cancer cell lines where the overall levels remained relatively stable and even increased at 16–24 h of CHX treatment." (PMID 21730980, 2011). "Dysfunctional STAT1 may contribute to cancer development and progression, while at the same time the ERK1/2 pathway regulates a common set of cell death regulators such as BCL-2, BCL-XL and BIM, indicating that it plays a role in cell cycle control." (PMID 21625390, 2011). "Therefore, TQ administration is a new approach that can enhance immunogenicity, reduce cell proliferation and increase apoptosis in cancer cells by suppressing STAT3 phosphorylation and Bcl-2/Bcl-XL expression." (PMID 22177381, 2011). "Unfortunately, insofar, there is no report to show the reason why a number of cancer cells can not be killed by Bcl-2 inhibitor." (PMID 21829603, 2011). "Finally, we have identified a number of down-regulated miRNAs whose targets are up-regulated in cancer, including the oncogenic protein KRAS and MYCN, mitogen-activated protein (MAP) kinases and the anti-apoptotic proteins BCL2, BCL2L2 and MCL-1 among others." (PMID 20668671, 2010). "Respectively, the rate of inhibition of EADM,5- Fu, NVB and DDP were significantly higher in the BCL-2 negative cancer cells than in the BCL-2 positive cancer cells." (PMID 20691103, 2010). "The balance between BCL-2 and BAD can effect the apoptosis of cancer cell." (PMID 20691103, 2010). "BCL2 (B-cell CLL/lymphoma 2) suppresses apoptosis, and the downregulation of BCL2 might be involved in the acceleration of apoptosis in cancer cells." (PMID 20628618, 2010). "Although the anti-apoptotic effect of Bcl-2 is well established, the role of Bcl-2 in cancer response to therapy and drug resistance has not been completely explored." (PMID 20403207, 2010). "In addition to IL-6, the expression of cyclin D1, c-myc, survivin, Bcl2, Mcl1, and VEGF, all of which are regulated by Stat3 activity, and play a crucial role in apoptosis and progression of cancer, are also down regulated in response to avicin D." (PMID 19440292, 2009). "Furthermore, BER shows synergistic effects with anticancer agents celecoxib, trichostatin A and carmofur on inhibiting the growth of MDA-MB-231 cells and reducing the ratio of Bcl-2/Bax and/or VEGF expressions in the cancer cells." (PMID 19796390, 2009). "There is an inverse correlation in the expression levels of miR-34 and Bcl-2 in Q2 versus Q3, e.g., Q2 cells (with enriched cancer stem cells) have high Bcl-2 and low miR-34, Q3 cells (non-tumorigenic cells) have low Bcl-2 and high miR-34 levels." (PMID 19714243, 2009).
cancer (continued). "In vitro, exposure of cancer cells to low, non-toxic doses of radiation resulted in the up regulation of Bcl-2, indicating these cells were attempting to adapt to the harmful environment." (PMID 19589167, 2009). "Whereas previous studies had shown that myc plus over-expression of Bcl-2 synergized to accelerate lymphomagenesis in the Eu-myc model, the genetic ablation of Bcl-2 had no impact on the cancer phenotype." (PMID 19209227, 2009). "Down-regulation of Bcl-2 protein levels and up-regulation of pro-apoptotic Bax protein expression are possibly the one of important mechanisms of action of BER induced apoptosis in the cancer cell." (PMID 19796390, 2009). "Bcl-2 and inhibitor of apoptosis (IAP) proteins have been investigated as potential therapeutic targets on the basis of their ability to disrupt apoptosis and to confer resistance to chemotherapy in cancer cells." (PMID 18373739, 2008). "The inhibition of antiapoptotic Bcl-2 and Bcl-XL, and induction of proapoptotic Bax, Bak, PUMA, Noxa, Bim, and Bid proteins by resveratrol suggest that the relative expression of these proteins can determine the sensitivity of cancer cells to TRAIL." (PMID 17718901, 2007). "Overexpression of Bcl-2, cytokeratins, and VEGF with downregulation of Bax, cytochrome C, caspase-3, caspase-9 and PARP may confer a survival advantage to HBP carcinomas by acquisition of an apoptosis-resistant, invasive and angiogenic phenotype." (PMID 18053169, 2007). "Infiltrating stromal lymphocytes also stained for BCL-2, irrespective of the BCL-2 status of the cancer cells, and served as positive internal controls." (PMID 11953819, 2002). "Moreover, we observed an upregulation of other STAT3 target genes, including BCL-XL and BCL2, following olaparib treatment that was abrogated upon STAT3 silencing, supporting the concept that cancer cells via STAT3 hijack the upregulation of survival effectors, as BCL-XL and BCL2." (PMID 41350901, 2025). "Moreover, it has been reported that cancer cells sustain hypoxia by upregulating the BCL2 interacting protein 3 (BNIP3)/BNIP3-like (BNIP3L), which in turn induces BECLIN-1 dependent autophagy by destabilizing Bcl-2-BECLIN-1 complex." (PMID 40917756, 2025). "In the context of cancer therapy, this dual role holds promise because it suggests that therapies aimed at enhancing ARTS function or mimicking its activity could simultaneously downregulate XIAP and Bcl-2, two critical anti-apoptotic proteins." (PMID 40841912, 2025). "Hence, antagonizing these antiapoptotic proteins is considered a reasonable approach to prevent cancer progression, where apoptosis inducers such as BH3‐mimetics act as effective anticancer drugs through specific binding to the hydrophobic groove of BCL‐2 antiapoptotic proteins." (PMID 40970582, 2025). "In contrast to these three main anti-apoptotic BCL2 proteins, the genes for the related anti-apoptotic BCL2 proteins Bfl1 (BCL2A1), BCL-w (BCL2L2) and BCL-B (BCL2L10) display little perturbation effects in cancer (mean Chronos Gene Dependency Scores −0.0454, −0.103 and 0.006, respectively)." (PMID 40113751, 2025). "This knowledge has been invaluable in guiding therapeutic strategies targeting BCL2 proteins, helping researchers anticipate potential side effects and refine approaches to selectively inhibit these proteins in cancer cells without disrupting essential functions in healthy cells." (PMID 40204952, 2025).
cancer (continued). "Therefore, it is not surprising that many cancer cells display genetic alterations leading to increased expression of one or multiple anti-apoptotic BCL2 proteins." (PMID 40113751, 2025). "Blocking anti-apoptotic BCL-2 proteins or boosting pro-apoptotic ones may make HTLV-1-infected T cells die, limit viral persistence, and support new therapies for ATLL and other HTLV-1 cancers." (PMID 41201565, 2025). "Indeed, cancer cells sustain hypoxia by upregulating the BCL2 interacting protein 3 (BNIP3)/BNIP3-like (BNIP3L), which in turn induces Beclin-1 dependent autophagy by destabilizing Bcl-2-Beclin-1 complex." (PMID 40917756, 2025). "In addition, HSP decreases Bcl-2, mitochondrial AIF, mitochondrial Apaf-1, and mitochondrial cyt-c, which drive cancer cell apoptosis, while upregulating a few intracellular ROS, ATP, Ca2+, and cytosolic components such as AIF, Apaf-1, cyt-c, caspase-3, caspase-9, and Bax." (PMID 40427522, 2025). "Mesothelin protects cancer cells from TNF-α-induced apoptosis by rapidly stimulating Akt phosphorylation under PI3K activation, inhibiting the expression of pro-apoptotic factors, such as Bad and Bax, and promoting the expression of anti-apoptotic genes, such as Bcl-2 and Mcl-1." (PMID 40227645, 2025). "While the rewiring of the BCL-2 interactome in senescent cells is thought to prime them for apoptosis, the universal use of pro-apoptotic BH3 mimetics as the senolytics of choice in “one-two punch” regimens remains uncertain due to the inconsistent responses observed in TIS cancer cells." (PMID 40055336, 2025). "Importantly, the specificity of our antibodies to the three major BCL-2 family heterodimer protein complexes (i.e., BCL-2, MCL-1, and BCL-XL with BIM) that dictate cancer cell priming was validated here using both purified proteins and cells, including knockdown/knockout lines." (PMID 40507334, 2025). "Additionally, the observed upregulation of pro-apoptotic genes such as BAX and Caspases in MCF-7, MDA-MB-231, T-47D, and U-937 cells, alongside minimal changes in BCL-2 in HSF cells, suggests that Brentuximab induces apoptosis preferentially in cancer cells while sparing normal fibroblasts." (PMID 39805861, 2025). "Cell cycle arrest induction and triggering apoptosis in cancer cell lines treated with BCP was reported to occur through upregulating reactive oxygen species (ROS), inducing mitochondrial dysfunction, activating caspases and Bax, or downregulating Bcl-2 in these cells." (PMID 40333803, 2025). "Among the mechanisms of cancer chemoresistance development metabolic reprogramming, in particular, autophagy enhancement, activation of cancer stem cells, activation of anti-apoptotic signaling (MAPK, PI3K-AKT, Notch, Wnt signaling), and production of anti-apoptotic proteins (i.e., Bcl-2) are noted." (PMID 38794298, 2024). "Increasing the expression of BCL-2 may be a compensatory mechanism of cancer cells, thanks to which apoptosis does not occur after reducing the activity of cytochrome C oxidase." (PMID 39063158, 2024).
cancer (continued). "Mechanistically, loss of FASN resulting in ETC inhibition may similarly increase BCL-2/BCL-XL dependency, thereby lowering the threshold for inducing apoptosis, making cancer cells easier to target for cytotoxic signals from CATs, and accelerating CAT-mediated killing." (PMID 39349429, 2024). "However, there are no previous data regarding the effect of MS17 on Bcl-2 protein expression in cancer cells." (PMID 38542474, 2024). "Thus, it can be reasonably expected that a clinical-grade DHODH inhibitor combined with venetoclax might improve outcomes for HGBCL patients, as well as other cancers with high expression of MYC and BCL2 or MYC and MCL-1." (PMID 38918775, 2024). "Intriguingly, the gene expression levels of BCL2, CDK2, MDM2, Casp9 and P21 were reversed in HeLa cells treated with L. cornuta ethyl acetate fraction when compared with the untreated HeLa cells, indicating its potential to regulate cell proliferation, apoptosis, and cell cycle in cancer cells." (PMID 39005932, 2024). "Additionally, compounds like 113 induced cell cycle arrest at the G1/G0 stage and promoted apoptosis through caspase-3 activation, downregulation of Bcl-2, and upregulation of Bax, suggesting a dual role of these compounds in both COX inhibition and cancer cell apoptosis." (PMID 39407697, 2024). "However, it has been reported that the overexpression of Bcl-2 and Mcl-1 in various hematologic cancers, including NHL, may lead to dysregulation of the apoptosis rate, benefiting cancer progression." (PMID 38731446, 2024). "Preclinical studies have shown that Oblimersen sodium reduces Bcl-2 expression, leading to cytotoxic and cytostatic effects in various cancer cells, including breast, ovarian, prostate, melanoma, non-small-cell lung carcinoma (NSCLC), bladder, and gastric cancers." (PMID 39594587, 2024). "Inducing apoptosis, stopping the G1 cell cycle, and inhibiting the growth of cancer cells are all possible at low concentrations of two important bioactiphores: indanone-derived SL and EGO The genes Bax/Caspase-3 and Bcl-2 were expressed more highly in SL analogs than in Bcl-2 types." (PMID 39683830, 2024). "On the contrary, thanks to its anti-cancer properties, SFN is able to induce apoptosis at higher doses as reported by Hussain and colleagues, who found an apoptosis induction in human breast cells through BCL-2 down-regulation after the treatment with 25 μM SFN." (PMID 39063113, 2024). "ALKBH5 demethylated the mRNA of Bcl-2 (B-cell lymphoma-2), which inhibits apoptosis, and increased its stability, thus promoting the interaction between Bcl-2 and Beclin1, inhibiting the autophagy of EOC and promoting the proliferation and invasion of cancer cells." (PMID 38343637, 2024). "Limonene also displayed proapoptotic effects in the T24 human bladder and HepG2 cancer cells by increasing Bax and decreasing Bcl2 expression, indicating that the apoptosis-dependent anticancer effect of these natural products is not restricted to a single cancer type." (PMID 38711049, 2024).
cancer (continued). "In addition, we observed that NR3C1 knockdown reinforced Bax expression and impaired Bcl-2 expression in cancer cells, while miR-1270 inhibitor reintroduction attenuated Bax expression that was reinforced by NR3C1 knockdown and recovered Bcl-2 expression that was impaired by NR3C1 knockdown." (PMID 36797317, 2023). "Together, these results define the Bcl-2 protein network critically involved in AURK inhibitor–induced apoptosis and suggest that BH3-mimetics targeting Bcl-xL may help overcome resistance to AURK inhibitors in cancer cells." (PMID 36621626, 2023). "We also found that the expression of BAX/Bcl-2 proteins, a pair of pro-apoptotic and anti-apoptotic proteins in cells that regulate apoptosis, significantly increased in B16F10 cells treated with MD@SA hydrogel, further supporting the evidence that the hydrogel induces apoptosis in cancer cells." (PMID 37981704, 2023). "While an independent role in cancer initiation is weak, Pim kinases show especially strong synergistic roles in the presence of other oncogenes, such as c-Myc/n-Myc (C/N-MYC Proto-Oncogene), and Bcl-2 (BCL2 Apoptosis Regulator) and in the presence of various carcinogens to initiate cancer." (PMID 36694243, 2023). "Defects in the intrinsic apoptotic pathway, owing to over-expression of pro-survival BCL-2 proteins or the abnormal reduction of pro-apoptotic BCL-2 family members, render both malignant as well as non-transformed cells profoundly resistant to a broad range of anti-cancer therapeutics." (PMID 36342579, 2023). "In turn, Bcl-2 (sometimes called master regulators of anti-apoptosis) not only promotes cancer cell proliferation and invasion but also allows the chemo- and immunotherapeutic resistance of cancer cells." (PMID 36993955, 2023). "Therefore, we explored the possibility that IMP3 could bind Bcl-2 and Bcl-xL mRNAs, known to be highly expressed in CRC tissue and with crucial role in cancer progression and therapy resistance." (PMID 37024466, 2023). "Furthermore, Bam HI fragment H rightward open reading frame 1 (BHRF1), one of the early proteins of the lytic cycle that is homologous to human Bcl2 anti-apoptotic protein, both in terms of genomic sequence and function, is able to inhibit apoptosis in EBV-infected cancer cells." (PMID 37736518, 2023). "In addition, there was a slight decrease in BCL-2 protein expression level in treated-cancer cells; however, the change was not significant." (PMID 37059982, 2023). "Besides this, HSP upregulated some intracellular ROS, ATP, Ca2+ and cytosolic components i,e AIF, Apaf-1, Cyt C, caspase-3, caspase-9, Bax, and down-regulated Bcl-2, mitochondrial AIF, mitochondrial Apaf-1, and mitochondrial Cyt C that mediate apoptosis of cancer cell." (PMID 35128104, 2022). "This suggests that EA.hy926 endothelial cells may have retained some characteristics of the A549 cancer cells, meaning they do not express BCL-2." (PMID 35805077, 2022). "Further in vitro experiments showed that TAX could significantly induce cancer cell apoptosis as verified by increased pro-apoptotic molecules including Bax, caspase-9, and PARP1 downregulated anti-apoptotic protein Bcl-2; and decreased mitochondrial potential." (PMID 36230568, 2022).